GLYATL1P4 (glycine-N-acyltransferase like 1 pseudogene 4)
Gene: Unprocessed pseudogene on chromosome 11 (59,042,737 to 59,050,971, forward strand). Ensembl gene ENSG00000254399.
Diseases named in the same sentence as GLYATL1P4 in open-access papers:
GLYATL1P4 is named in the same sentence as 2 diseases in open-access papers, as found by Europe PMC text mining. Sharing a sentence is not in itself a finding about the gene and the disease. The quoted sentences say what the papers report.
cancer (1 paper, 2019). A tumor composed of atypical neoplastic, often pleomorphic cells that invade other tissues. "Notably, the GLYATL1P4 transcript makes part, together with 21 other RNAs, of the Decipher test proposed in clinics to guide timing of radiation therapy after radical prostatectomy in men with high-risk cancer." (PMID 31732695, 2019).
GLYATL1P4 also shares sentences with these, for which no sentence is quoted: prostate carcinoma (1 paper).